MMP1 (matrix metallopeptidase 1)
Diseases named in the same sentence as MMP1 in open-access papers (continued):
Sharing a sentence is not in itself a finding about the gene and the disease.
tumor (continued). "The results indicated that the MMP1 expression was significantly higher in tumor samples compared with normal samples at mRNA level." (PMID 29207651, 2017). "The tumour inhibitory mechanism of LINC00312 was supposed to down-regulate the expression of oestrogen receptor alpha (ER-alpha) by regulating the JNK2/AP-1/MMP1 pathway." (PMID 28404955, 2017). "We observed constitutively elevated levels of cytokines MCP-1, G-CSF, and RANTES in tumor cells, and of IL-1β, IL-8, MMP-1, MMP-2, and MMP-10 after co-culture." (PMID 28337194, 2017). "We also found that the interaction of tumor cells with monocytes promoted high levels of matrix metalloproteinases (MMP)-1, MMP-2, and MMP-10." (PMID 28337194, 2017). "We detected that MMP1 overexpression in BC significantly correlated with tumor size (p=0.001), ER (p=0.005) and PR (p=0.027) status." (PMID 29207651, 2017). "Mmp1 degrades the basement membrane of the imaginal disc, allowing tumor cell migration and invasion." (PMID 28754838, 2017). "MMP1 has been widely reported to be involved in tumour invasion; however, its regulation of cell apoptosis and proliferation has not been well covered in the literature." (PMID 28262842, 2017). "Studies of normal cell migration and tumor cell invasion demonstrate that MMP-1 expression influences actin remodeling during cell movement." (PMID 28825401, 2017). "Tumor-endothelial cross-talk via an intravascular MMP-1/PAR-1 axis exists in microvascular and macrovascular endothelium." (PMID 29291033, 2017). "MMP-1 has proved to be a tumor growth promoting and pro-angiogenic factor in the lungs of MMP-1-deficient mice." (PMID 29207990, 2017). "Consistent with the role of tumor cell-derived MMP-1 in endothelial permeability and transendothelial migration, both of these are reduced in MLK3-depleted TNBC cells." (PMID 28604765, 2017). "Strikingly, overexpression of bskDN also reduced Mmp1 levels 4.1-fold (P<0.01) in GFP-labelled tumour cells and also almost completely blocked RasV12/pico-mediated tumour cell invasion of the VNC." (PMID 28346426, 2017). "First we have checked the tumor cells reactivity for the main MMPs (MMP-1, −2, −3, −4) known to be involved in extracellular matrix remodeling." (PMID 27871286, 2016). "Similar to MMP-2, the collagenases MMP-1 and MMP-13 are expressed in stromal cells, particularly in tumor-associated fibroblasts." (PMID 27271600, 2016). "We found that PMA (50 ng/mL), which is a strong tumor inducer, significantly enhanced MMP-1, -3, and -9 mRNA expressions, whereas pre-treatment with C2 ceramide resulted in an inhibition of the MMP-1, -3, and -9 expressions in both the U87MG and U373MG cells." (PMID 27043542, 2016). "MMP-1 gene expression is stimulated at the transcriptional level by various cytokines, growth factors and tumour promoters via a promoter segment, which contains adjacent binding sites for ETS and AP-1 transcription factors." (PMID 27412967, 2016). "In our study, we also found that the Immunostaining of MMP1 was stronger in tumor cells than in adjacent normal parts in the two ESCC patients." (PMID 27436512, 2016). "To explore the mechanism behind the antitumor activity of grifolin, we performed a screening of genes related to tumor adhesion/invasion regulation, including MMP1,2,3,9,19, TIMP-1,2,3, CD44, CDH1 and PCDH10." (PMID 27626695, 2016). "The minimum, mean, and maximum values of tumor/normal (T/N) MMP1 expression ratios were 3.23, 213.39, and 1148.64 respectively." (PMID 27436512, 2016). "MMP-1 protein cleaves interstitial collagens in the extracellular matrix, thus facilitating tumor invasion." (PMID 26800519, 2016). "In this study, we chose to investigate MMP-1 and VEGF as indicators of the interaction between tumor and stromal cells, because both have been clearly linked to tumor invasion and metastasis." (PMID 27232698, 2016). "MMPs were reported to induce tumor progression in HCC including MMP-1, MMP-2, MMP-3, MMP-7, MMP-9, MMP-11 and MMP-13." (PMID 26882566, 2016).
tumor (continued). "MMP1 is a member of MMPs, which exerts key functions in tumor invasion and metastasis in many cancers." (PMID 27034707, 2016). "The future study should collect a serial measurement of MMP1 along with treatment (or cancer relapse) to further confirm its role as a tumor marker." (PMID 27436512, 2016). "Ninety-eight percent of the patients (52/53) in the GSE23400 dataset had higher expression of MMP1 in tumor tissues than normal tissues." (PMID 27436512, 2016). "With 21D1−MMP1 cells displaying reduced oncogenicity in vitro, we next measured the impact of MMP1 knock-down on 21D1 cell tumour xenografts in vivo." (PMID 27324842, 2016). "Tumor-derived MMP-1 has also been shown to activate PAR, resulting in acute endothelial cell activation, and pro inflammatory signals." (PMID 25664615, 2015). "In our study, depletion of p62 even results in the accumulation of several tumour-promoting factors, including MMP1, MT-MMP and Twist." (PMID 26268733, 2015). "Considering that NF-κB triggers many extracellular events like tumor angiogenesis, it is very likely to have a relation with MMP-1." (PMID 25945089, 2015). "It has been well documented that CD147 induces the expression of several MMPs, such as MMP-1, MMP-2, MMP-9, which are associated with tumor migration and invasion." (PMID 26507719, 2015). "In our xenograft model with A549, curcumin can significantly decrease tumor growth and has a similar suppressing effect of the expression of MMPs, except for MMP-1 and -13." (PMID 26656720, 2015). "These tumor suppressive functions were paralleled at the molecular level by concomitant down-regulation of self-renewal (Bmi-1and Oct4A) and invasion related (MMP1 and MMP9) molecules in vitro." (PMID 26353754, 2015). "In conclusion, our results show that although Ftz-F1 and Fos are both required for invasiveness of rasV12scrib1 tumors, these TFs were unable to promote malignant tumor overgrowth or MMP1 expression on their own or when combined with RasV12." (PMID 26398940, 2015). "Third, we found that DSF effectively inhibited tumor cell migration and invasion through modulation of MMP-1 and MMP-3 expression." (PMID 26517513, 2015). "Studies on the SUM149 IBC cell line actually demonstrated that the invasive nature of IBC tumour cells critically depends on the overexpression of functional E-Cadherin and the influence thereof on MMP1 and MMP9 expression." (PMID 24586640, 2014). "A number of ECM degrading MMPs, such as MMP1, MMP2 and MMP14, have been implicated in the process of tumor invasion and metastasis." (PMID 25349534, 2014). "Similar to other Drosophila tumor models we found that Ras-expressing glands produce matrix metalloproteinases (matrix metalloproteinase 1: MMP1), while imaginal discs from the same animals showed very little if any signs of expressing MMP1." (PMID 24659248, 2014). "Among the studied genes, the overexpression of the following metalloproteinases in the tumor tissue can be correlated to at least one clinicopathological variable: MMP-1, MMP-2, MMP-9, MMP-11, and MMP-16." (PMID 24737953, 2014). "Specifically, high expression of tumor-derived PDGF-BB and MMP-1 were associated with increased cancer survival (p < 0.05), while high expression of MMP-2 showed a trend towards improved outcome (p = 0.058)." (PMID 25483099, 2014). "The most significant up-regulated genes identified in this tumor model are related to chromosome-end replication (Tert), invasion and metastasis (Plau, Serpine1, Mmp9 and Mmp1), cell adhesion (Itgb3 and Itgav) and angiogenesis (Angpt1 and Vegfa)." (PMID 24928374, 2014). "MMP-10 is considered an important factor in the activation of other MMP (such as MMP-1) precursors in human tumor cells." (PMID 25120597, 2014). "MMP-1 is predominantly involved in the degradation of stromal components, and is important in tumor invasion and metastasis." (PMID 25120597, 2014).
tumor (continued). "The thrombin receptor PAR-1 has now been shown to be cleaved and activated on the tumor cell surface by stromal-derived MMP1." (PMID 24804002, 2014). "For example, several associations between neoplasm-related ADRs and known tumor suppressor (Syk) and tumor invasiveness marker (MMP-1 and C3) proteins are found." (PMID 25191698, 2014). "MMP-1 is secreted by MSCs as they migrate towards tumours, and having reported here that MPs induce both chemotaxis and MMP-1 expression in MSC, it appears that MPs are particularly supportive of MSC migration." (PMID 25250510, 2014). "We identified multiple genes that were induced or repressed upon P4HA1 knockdown including those involved in tumor growth and invasion such as MMP1, MMP2 and FLRT3, among others." (PMID 25115393, 2014). "Our translational data are consistent with these observations and further support role of MMP1 in tumor self-seeding." (PMID 24972610, 2014). "MMP-10 is considered to be the most important factor in human tumor cells that can activate other MMP (such as MMP-1) precursors." (PMID 25120597, 2014). "In vivo, MMP-1 knockdown significantly decreased osteoclast recruitment to tumor bone interface, leading to a decrease in bone resorption and consequent decrease in bone osteolysis, smaller x-ray osteolytic lesions, and a decrease in tumor burden." (PMID 23696795, 2013). "Microbial infection in this case increases the metastatic potential of the tumor by increasing the number of JNK/MMP1 positive cells, thereby further compromising the integrity of the tissue and facilitating the migration of dRas1V12 transformed cells." (PMID 24392358, 2013). "Several studies demonstrated that enhanced MMP-1 expression increased angiogenic activity in tumors, and that tumor-derived MMP-1 stimulates endothelial cell activation and promotes complex tube formation in vitro." (PMID 24392031, 2013). "In vivo, MMP-1 knockdown resulted in smaller x-ray osteolytic lesions and osteoclastogenesis, and decreased tumor burden." (PMID 23696795, 2013). "Using a mouse model of bone metastasis, we demonstrated that MMP-1 knockdown significantly decreased bone osteolysis and osteoclast recruitment to the tumor-bone interface, and also decreased tumor burden." (PMID 23696795, 2013). "More recently, in a study with 92 patients with bone metastasis from solid tumors, we demonstrated that MMP-1 was expressed in most cases, independently of tumor type, X-ray pattern of bone lesions, and previous bisphosphonate therapy." (PMID 23696795, 2013). "Evaluation of tumor grade showed that women with the MMP1 rs17293761 TT genotype were less likely to have a poorly differentiated tumor than a well differentiated tumor (OR 0.06, 95% CI<0.01–0.46; padj 0.045)." (PMID 23696797, 2013). "In Dittmer study reported that over-expression of ETS1 would promote tumor invasion due to its ability to activate the MMP1, MMP3, MMP9 and uPA as well as of VEGF in tumorigenesis." (PMID 23405089, 2013). "In summary, MMP1 contributes to tumor invasion and metastasis by remodeling the matrix, and triggering the signaling cascades and crosstalk between neoplastic cells and adjacent interstitium." (PMID 24063540, 2013). "The tumor infiltrating M2 macrophages promote the matrix remodeling process through increased MMP-1 activation." (PMID 24278120, 2013). "MMP-1 is an interstitial collagenase that is often upregulated in several types of cancer, and this enzyme is involved in tumor-induced angiogenesis." (PMID 24392031, 2013). "Immunohistochemical analysis also indicated that the JNK target, Mmp1, was ectopically expressed within scrib−+ab tumours, and, in agreement with the expression array, Mmp1 levels were also slightly elevated in ab alone overexpressing clones." (PMID 23874226, 2013).
tumor (continued). "CD204(+) macrophages reportedly exhibit a tumor-promoting function in several tumors by secreting matrix metalloproteinase (MMP)-1, MMP-3, MMP-7, MMP-9, MMP-12, vascular endothelial growth factor (VEGF), and transforming growth factor (TGF)-β." (PMID 24376714, 2013). "In contrast to these well characterized functions of MMP-1 in tumor progression, its role in brain metastasis has received less attention." (PMID 23217186, 2012). "Many reports have shown that MMP-1 can promote tumor growth and metastasis through catalyzing extracellular matrix and by promoting angiogenesis." (PMID 23217186, 2012). "MMP-1 is expressed by a variety of tumor cells, where its levels are constitutively high even in the absence of apparent external stimuli." (PMID 22415590, 2012). "Real-time PCR quantification using RNA isolated from tumor tissues confirmed the continued silencing of MMP-1 in vivo." (PMID 23217186, 2012). "Reducing the expression of MMP-1 with shRNA attenuated tumor growth in the mammary fat pads and reduced invasion through matrix-coated filters of the 231-BR and 231-BR3 cells, similar to the findings of other investigators using non-selected MDA-MB-231 cells." (PMID 23217186, 2012). "Immunohistochemical analysis of tumor sections also demonstrated reduced staining for MMP-1 in sh1 and sh1b tumors compared with tumors of the control cell lines." (PMID 23217186, 2012). "The potential independent prognostic value of MMP-1 protein expression in tumour cells was evaluated by stepwise Cox regression analysis." (PMID 21835023, 2011). "In a multivariate analysis the presence of MMP-1 positivity in tumour cells had an independent prognostic value as did Ki-67 and bcl-2 immunoreactivity." (PMID 21835023, 2011). "In tumour cells the MMP-1 expression was positive in 7.2% with value ≤ 30%, in 8% with value ≤ 50%, in 31.2% with value ≤ 70% and in 53.6% with value over 70%." (PMID 21835023, 2011). "Further investigation with larger patient cohorts is needed to better understand the function of MMP-1 in tumour cells." (PMID 21835023, 2011). "A positive correlation was seen between tumour grade and MMP-1 expression in tumour cells (r = 0.23, p = 0.0101) and in stromal cells (r = 0.21, p = 0.0170), the higher grade tumours showing stronger MMP-1 positivity." (PMID 21835023, 2011). "The most important finding of this study was the independent prognostic value of MMP-1 as well as Ki-67 and bcl-2 expression in tumour cells." (PMID 21835023, 2011). "Earlier studies have demonstrated elevated nuclear MMP-1 expression in tumour cells, as well as in stromal fibroblasts." (PMID 21835023, 2011). "In previous studies high expression on MMP-1 by stromal cells correlated with the occurrence of metastasis suggesting that tumoural stromal tissue is important in cancer progression." (PMID 21835023, 2011). "HER2 immunoreactivity correlated with MMP-1 positivity both in stromal cells (r = 0.25, p = 0.0050) and tumour cells (r = 0.22, p = 0.0121)." (PMID 21835023, 2011). "Positive correlations were found between tumour grade and MMP-1 expression in tumour cells and in stromal cells." (PMID 21835023, 2011). "Protease-Activated Receptors can also signal in response to proteases that stem from the tumor and the tumor microenvironments such as MMP-1." (PMID 21378407, 2011). "Analysis of vascularity revealed a statistically significant increase in mean vascular volume per unit volume of tumor for MMP1 silenced group (321233±41140 threshold pixels) as compared to control (184283±78021 threshold pixels) group (p = 0.01)." (PMID 21170377, 2010).
tumor (continued). "Nevertheless, we observed a strong increase of pro-MMP-9 secretion in EDPs-treated tumours and, more importantly, an increase in the expression and activation of the murine counterpart of MMP-1, named murine collagenase-A (Mcol-A)." (PMID 20959825, 2010). "These cell lines were subsequently injected in animals to investigate the role of MMP1 silencing on tumor progression." (PMID 21170377, 2010). "In an attempt to understand the effects of MMP1 gene silencing on primary tumor growth, tumor vascularity was assessed." (PMID 21170377, 2010). "A xenogenic model of tumor progression was then used and mice were divided in two groups: each harboring either the control or a stably MMP1 silenced cell line." (PMID 21170377, 2010). "A critical role of MMP-1 for promoting invasion and metastasis in this tumor entity has been described earlier." (PMID 20946664, 2010). "Prior clinical trials employing MMP1 inhibitors failed because of a poor understanding of the role of MMPs in tumor progression." (PMID 21170377, 2010). "The tumor containing MMP1 silenced cells demonstrates increased vascularity and increased number small vessels approaching the tumor cells." (PMID 21170377, 2010). "The range of difference in expression of MMP1 between tumor cells and stromal cells after normalization ranged from 4 -fold to a 100-fold difference." (PMID 21170377, 2010). "Further analysis revealed that MMP1 silenced group had a constant rate of tumor growth over 5 weeks whereas mice bearing control group showed a plateau in tumor growth over time." (PMID 21170377, 2010). "Repeating the experiment using a a second shRNA sequence and subsequent MMP1 silenced tumor cell clone allows verifies that findings reported are real and not a result of clonal variation or artifact." (PMID 21170377, 2010). "This is the first report of localized pro-tumorigenic effects of MMP1 silencing and more importantly the first report of opposing effects on local growth versus systemic tumor burden of MMP1 in an animal model of metastasis." (PMID 21170377, 2010). "To analyze differences in tumor related survival dependent on MMP-1-expression in EAC we divided the patients in two subgroups (dichotomous variables)." (PMID 20946664, 2010). "The stage of tumor progression is positively correlated with the expression of MMP family members (MMP-1/interstitial collagenase; MMPs 2, 3, 7, 9, 11, and 14)." (PMID 21152266, 2010). "Not only does metastasis seem to be affected by MMP1 silencing, but also local tumor growth and angiogenesis are affected inversely." (PMID 21170377, 2010). "This corroborates previous studies and that the observed difference in expression of MMP1 between host and tumor cells is genuine; and the populations of cells collected for analysis from the tumor and stromal aspects of the tumor were comparable." (PMID 21170377, 2010). "The percentage lung metastatic volume at 5 weeks (p = 0.08) and number of spontaneous deaths secondary to systemic tumor burden were lower in MMP1 silenced cell bearing mice." (PMID 21170377, 2010). "The precise cellular and molecular mechanisms of MMP1 silenced cells leading to increase in local tumor growth; angiogenesis and a lower pulmonary burden are currently being pursued." (PMID 21170377, 2010). "The candidate gene, matrix metalloproteinase one or MMP1, was found to be highly upregulated in highly migratory MSCs that exhibited the tumor trophic property and was chosen for subsequent studies." (PMID 19489099, 2009). "Using substrate zymography, MMP-1, -2, -3 and -9 demonstrated a higher activity in tumor tissues compared to healthy samples." (PMID 19531263, 2009). "For MMP-1 the staining showed a clear predominance for the nuclei of tumor cells with a slight additional staining in the tumor cell's cytoplasm." (PMID 19531263, 2009).